CSPG4 (chondroitin sulfate proteoglycan 4)
Diseases named in the same sentence as CSPG4 in open-access papers (continued):
Sharing a sentence is not in itself a finding about the gene and the disease.
melanoma (continued). "Furthermore, in silico analysis found other genes upregulated in the CSPG4-enriched population to be connected to metastasis, tumor growth, and melanoma biology, which indicates an interesting biological role of CSPG4-positive CTCs for melanoma progression." (PMID 32984308, 2020). "CSPG4+ MTEX captured from the plasma of melanoma patients are highly enriched in melanoma-associated antigens (MAA) in comparison to CSPG4(-) non-MTEX, including CSPG4, TYRP2, MelanA, Gp100, VLA4." (PMID 32709086, 2020). "Moreover, CSPG4 is expressed in a majority of melanoma lesions and is a well-characterized surface marker for melanoma." (PMID 32984308, 2020). "In addition there was differential in vitro elimination of both BRAF inhibitor sensitive and resistant melanoma cells by B7-H3- or CSPG4-specific CAR T cells." (PMID 32894202, 2020). "On the other hand, when we investigated the tumor cell killing effects of anti-CSPG4-(PDD) in CSPG4-high expressing A375 and CSPG4-low expressing WM-1361 melanoma cells, we observed a time- and target-antigen dependent loss in proliferation in anti-CSPG4-(PDD)-exposed cells compared to PBS controls." (PMID 32331483, 2020). "The protocol for the generation of CAR-mRNA-transfected T cells described here is highly feasible, highly reproducible, and performed at a clinical-scale under full GMP compliance, and will be used for a clinical trial with CSPG4-specific CAR-T cells in melanoma patients." (PMID 31426437, 2019). "As expected, CSPG4-expressing A375M melanoma cells evoked TNF production by CSPG4-CAR T cells." (PMID 31195686, 2019). "In this study we describe the establishment of the clinical-scale production of CAR-T cells for the treatment of melanoma patients by mRNA transfection of a CSPG4-specific CAR under full GMP compliance in direct preparation of a clinical trial using these cells." (PMID 31426437, 2019). "Dogs with stage II and III surgically resected CSPG4-positive oral malignant melanoma were subjected to monthly intramuscular plasmid administration, which was followed immediately by electroporation (electrovaccination) to increase immunogenicity from six to 20 months." (PMID 30759787, 2019). "Besides the issues with potential on-target/off-tumor activities, which are discussed in detail in the melanoma section, the heterogenous expression of CSPG4 on leukemia cells remains a critical challenge." (PMID 31779130, 2019). "Moreover, CSPG4 displays a broad expression across several different cancer entities, such as melanoma, leukemia, glioma, triple-negative breast cancer, head and neck cancers, and mesenchymal cancers." (PMID 31779130, 2019). "Interestingly, anti-CSPG4 antibodies are already being used for the capture and detection of circulating melanoma cells." (PMID 31466397, 2019). "Finally, concerns raised by potential on-target/off-tumor toxicities, which are discussed in detail in the melanoma section, also apply to CSPG4-CAR-T-cell therapy of TNBC." (PMID 31779130, 2019). "Moreover, CSPG4-CAR T cells exhibited IFNγ production upon co-culture with human melanoma cells A375M, serving as positive controls." (PMID 31195686, 2019). "Taken together, CSPG4 expedites melanoma progression in myriad ways and thus, CSPG4 may be less prone to antigen-loss during CAR-T-cell therapy." (PMID 31779130, 2019). "Targeting CSPG4 using monoclonal antibodies decreases mesothelioma cell invasiveness as well, and it has been proposed as a potential target for the treatment of mesothelioma, breast cancer, and melanoma." (PMID 30333973, 2018). "NG2/CSPG4 was first characterized as a high-molecular-weight type 1 membrane proteoglycan in rat in 1981, and then identified with a mouse monoclonal antibody (mAb) on human melanoma cells." (PMID 30213051, 2018).
melanoma (continued). "The CSPG4 antigen (the melanoma-associated chondroitin sulfate proteoglycan, MCSP, or the high molecular weight melanoma-associated antigen, HMW-MAA) is expressed in 90% of melanoma lesions and other malignancies (e.g., sarcomas and gliomas)." (PMID 30103488, 2018). "The complete sequence of CSPG4 expressed by human melanoma cells was published in 1996: the gene, located on chromosome 15:24q2, is composed of 10 exons and the cDNA sequence length is of 8071 base pair (bp) encoding an open reading frame of 2322 amino acids (aa)." (PMID 28668095, 2017). "Finally, as already shown for human tumors, it is likely that CSPG4 is expressed by other canine tumor histotypes besides malignant melanoma." (PMID 28668095, 2017). "CSPG4 expression on tumor cell membrane has been confirmed by flow cytometry analysis in all the canine melanoma cell lines analyzed (unpublished data), thus representing an interesting tool for the in vitro study of CSPG4 in a canine melanoma model." (PMID 28668095, 2017). "In addition to the impact of CSPG4 on aggressiveness of melanoma, matrix metalloproteinase (MMP)-2, or gelatinase A, has also been associated with increased invasiveness of malignant melanoma, due to effects on the degradation of the extracellular matrix." (PMID 27926479, 2017). "Since a big proportion of melanomas feature constitutively active MAPK pathway due to mutations in the gene encoding the serine/threonine-protein kinase, BRAF, several groups have investigated the effect of CSPG4 in BRAF mutant melanoma in vitro." (PMID 29375561, 2017). "These preliminary findings suggest that combining anti-CSPG4 antibodies with pathway inhibitors may enhance the restricted success of BRAF inhibitors in melanoma." (PMID 29375561, 2017). "In this way they revealed that melanoma lesions can be efficiently eradicated through the specific T cell-mediated elimination of a definite melanoma cell population, highlighting the fundamental relevance of CSPG4 targeting." (PMID 28668095, 2017). "Both CSPG4 and MMP2 have previously been implicated in melanoma progression." (PMID 27926479, 2017). "In support, immunohistochemistry data evaluating CSPG4 expression in human melanoma claim higher levels in metastatic lesions than in primary tumors, and CSPG4 mRNA expression was reported to be predictive of metastasis formation in soft tissue sarcoma patients." (PMID 29375561, 2017). "Melanoma cells were treated with polyclonal anti-CSPG4-antibodies and vemurafenib." (PMID 25997619, 2015). "Therapeutic targeting of CSPG4 in melanoma and glioblastoma appears to yield anti-tumor effects." (PMID 24932730, 2014). "CSPG4 could be an attractive immunotherapy target given its expression on a high percentage of melanomas as well as many other cancer histologies and cancer stem cells." (PMID 25197555, 2014). "CSPG4 is thought to play crucial roles in cell adhesion, melanoma migration, and metastasis." (PMID 25667918, 2014). "An anti-CSPG4 scFv antibody fragment fused with human TRAIL (TNF-related apoptosis-inducing ligand) was designed to deliver pro-apoptotic TRAIL-signalling activity when bound to CSPG4+ melanoma cells, while inhibiting antitumourigenic signalling via CSPG4 downstream signal blocking." (PMID 24969320, 2014). "In addition to melanoma cells, CSPG4 is expressed at high levels in tumour angiogenic vasculature, providing the potential for a targeted therapy to also restrict tumour blood supply." (PMID 24969320, 2014). "CSPG4 has significant potential as an immunotherapy target, as supported by its expression on a high percentage of melanomas and its prevalence in other cancer histologies and CSCs, as well as, its general lack of expression on normal tissues as demonstrated by immunohistochemistry." (PMID 25197555, 2014). "CSPG4 is also present in melanoma and promotes tumor invasion and metastasis." (PMID 24205138, 2013).
melanoma (continued). "The association of these membrane glycoproteins with MMP-2 activation is of particular interest because αvβ3 integrin is often highly expressed on melanoma, claudin-1 expression levels increase with increasing thickness of the primary lesion and CSPG4 is potentially a useful biomarker for melanoma." (PMID 24069584, 2013). "Another mechanism by which CSPG4 facilitates melanoma metastasis is by its interaction with MMP-2." (PMID 24069584, 2013). "Aberrant expression of the progenitor marker Neuron-glia 2 (NG2/CSPG4) or melanoma proteoglycan on cancer cells and angiogenic vasculature is associated with an aggressive disease course in several malignancies including glioblastoma multiforme (GBM) and melanoma." (PMID 21829586, 2011). "Together these results suggest that CSPG4-targeting CAR-Ms may reduce melanoma growth in vivo." (PMID 40082557, 2025). "In addition, similar levels of CSPG4 expression were observed in melanoma metastases." (PMID 40700516, 2025). "Thus, we focused our efforts on improving CAR-M-mediated phagocytosis of melanoma cells by engineering the CSPG4-targeting chimeric antigen receptor to contain the intracellular FcRγ phagocytic signaling domain and combining the CSPG4-targeting CAR-Ms with CD47 blocking antibodies." (PMID 40082557, 2025). "Importantly, CSPG4-targeting CAR-Ms inhibited melanoma tumor growth in mouse models." (PMID 40082557, 2025). "Furthermore, we show that CSPG4-targeting CAR-Ms inhibit melanoma growth in vivo." (PMID 40082557, 2025). "The expression pattern of CSPG4 combined with putative roles in multiple oncogenic and treatment resistance-promoting pathways render this a promising target for cancer therapies that are designed to inhibit its pro-tumour functions or focus immune responses against CSPG4-expressing melanomas." (PMID 39409881, 2024). "Chondroitin sulfate proteoglycan 4 (CSPG4), also known as melanoma-associated chondroitin sulfate proteoglycan (MCSP) or neuron-glia antigen-2 (NG2) in mice and rats, is a transmembrane protein, first described over 40 years ago, which is highly expressed on human melanoma cells." (PMID 39409881, 2024). "Finally, in patient-derived subcutaneous melanoma xenografts engrafted with autologous immune cells from the same patient, we observed significantly longer survival of mice receiving CSPG4 IgE, compared to controls treated with the patient’s immune cells alone." (PMID 37185332, 2023). "The intense expression of CSPG4 by all our patient-derived melanoma cell lines was observed regardless of the HLA deficiency degree and allowed the strong CAR.CIK-mediated killing, even in challenging conditions of high tumor cell density (low effector to target ratios)." (PMID 37993874, 2023). "In this study, we investigated the preclinical activity of patient-derived CSPG4-CAR.CIK against patient-derived melanoma cells, focusing on models with defective expression of HLA-I molecules, as this setting might provide a representative perspective of the challenging clinical scenario." (PMID 37993874, 2023). "Furthermore, CSPG4 gene expression was measured across primary and metastatic disease (skin, visceral and lymph node metastases) (left, n = 36–208), and across all stages of melanoma (right)." (PMID 37185332, 2023). "Importantly, CSPG4 is a very well-established target antigen in melanoma, and we could previously demonstrate that T cells engineered to target CSPG4 could reliably kill CSPG4-positive melanoma cells." (PMID 36291817, 2022). "Therefore, to diagnose cancer based on a transparent relationship with cancer, such as the case where melanoma-derived exosomes were detected in bodily fluid samples based on the CSPG4 protein expressed in melanoma, phenotypic issues need to be specified prior to experimentation." (PMID 36005042, 2022).
melanoma (continued). "CSPG4 is overexpressed in many tumor samples, while its expression in normal tissue samples is substantially lower, which makes it a possible target for immunotherapy of several malignancies, including melanoma, triple-negative breast cancer, mesothelioma, and others." (PMID 36186476, 2022). "Indeed, MTEX were found to carry a profile of several melanoma associated antigens (MAAs), including CSPG4, while non-MTEX did not carry MAAs." (PMID 34207762, 2021). "TAAs identified in melanoma include vascular endothelial growth factor receptor 2 (VEGFR2), gp100, TRP-1, TRP-2, GD2, L1-CAM, cancer/testis antigen 1B and melanoma-associated chondroitin sulfate proteoglycan (MCSP; also referred to as chondroitin sulfate proteoglycan 4 (CSPG4))." (PMID 32899932, 2020). "Similarly, antibody-drug conjugate targeting CSPG4 triggered melanoma regression in vivo." (PMID 33330449, 2020). "In addition to CSPG4, other melanoma-specific or enhanced proteins might also be considered as potential markers of MTEX." (PMID 32709086, 2020). "Indeed, initial longitudinal study of CTC heterogeneity in 10 stage IV melanoma patients suggested that expression of CSPG4 on CTCs may be downregulated in response to BRAF and mitogen-activated protein kinase kinase (MEK)-inhibiting therapy." (PMID 32984308, 2020). "Furthermore, originally named as melanoma-associated chondroitin sulfate proteoglycan upon its cloning, NG2/CSPG4 has since been widely implicated in a wide variety of human cancers both as a diagnostic marker and a therapeutic target, including for glioblastoma and melanoma." (PMID 29302076, 2019). "Similarly to melanoma, CSPG4 exerts pro-oncogenic functions in GBM, fostering tumor growth." (PMID 31779130, 2019). "Therefore, it was our aim in this study to establish the clinical-scale production of CAR-T cells for the treatment of melanoma patients by mRNA transfection of a CSPG4-specific CAR under full GMP compliance, in direct preparation of a clinical trial using these cells." (PMID 31426437, 2019). "The CSPG4 antigen (chondroitin sulfate proteoglycan 4, also known as melanoma-associated chondroitin sulfate proteoglycan, MCSP, or high molecular weight melanoma-associated antigen, HMW-MAA) is expressed in 90% of melanoma lesions and other malignancies, e.g., gliomas and sarcomas." (PMID 31137488, 2019). "Thus, early onset cytokine release syndrome upon infusion of CSPG4-CAR T cells might be more frequent in leukemia than in melanoma." (PMID 31195686, 2019). "Moreover, we have evaluated the presence of CSPG4 on different cell lines generated from three canine melanoma patients: one named OLGA, generated starting from the bioptic material obtained from a metastatic lymph node, and two lines named CMM9 and CMM10, derived from primary oral melanomas." (PMID 28668095, 2017). "Also in those melanomas in which the BRAFV600E mutation determines a constitutive activation of the downstream MAPK pathway positively impacting on cell proliferation, the expression of CSPG4 is required to maximize the tumorigenic effect." (PMID 28668095, 2017). "Importantly, these peptide-specific CD4+ T cells could strongly recognize CSPG4 expressing melanoma cells, suggesting that the identified peptides are naturally processed by tumor cells." (PMID 28668095, 2017). "With this in mind and considering the well-known link between CSPG4 expression and melanoma progression in humans, other than the urgent need of effective strategies for the treatment of both human and canine melanomas, we were the first to evaluate CSPG4 expression in canine malignant melanomas." (PMID 28668095, 2017). "Finally, therapeutic CSPG4-directed cancer cell death may also be achieved using a bsAb-based approach as is exemplified by bsAb MCSPxDR5 that can exert strong and selective DR5-dependent cytotoxic activity against CSPG4-expressing melanoma cells." (PMID 28657611, 2017).
melanoma (continued). "Therefore, bsAb MCSPxDR5 may be of value for the targeted treatment of melanoma and other CSPG4-expressing malignancies." (PMID 28657611, 2017). "The CSPG4-specific monoclonal antibody 225.28 was shown to induce regression of tumor metastases, to inhibit spontaneous metastasis and tumor recurrence in breast cancer mouse models, and to inhibit the growth and recurrence of melanoma in a human melanoma xenograft model." (PMID 25997619, 2015). "However, a recent study reported that a cytoplasmic form of the protein appears to correspond with response to treatment with a melanoma vaccine, indicating that CSPG4 may potentially be evaluated as a marker of response or progression." (PMID 25667918, 2014). "From these reviews and others we have identified five melanoma biomarkers consistently associated with melanoma progression – melanoma cell adhesion molecule (MCAM), galectin-3 (Gal-3), matrix metalloproteinase-2 (MMP-2), chondroitin sulfate proteoglycan 4 (CSPG4), and paired box 3 (PAX3)." (PMID 24069584, 2013). "Using CSPG4 as the target melanoma antigen, our findings demonstrate that CAR-Ms efficiently phagocytose metastatic melanoma cells." (PMID 40082557, 2025). "In melanoma models, CAR-NKT cells targeting chondroitin sulfate proteoglycan 4 (CSPG4) demonstrated superior tumour elimination compared to CAR-T cells, with faster expansion rates and enhanced infiltration into TME ​." (PMID 40624498, 2025). "Another target is chondroitin sulfate proteoglycan 4 (CSPG4), a transmembrane proteoglycan initially identified as an immunogenic tumor antigen on the surface of melanoma cells." (PMID 40700516, 2025). "In our previous studies, a CSPG4‐specific CAR was developed, enabling antigen‐specific melanoma cell lysis and release of proinflammatory cytokines." (PMID 39764559, 2025). "We demonstrate that CSPG4-targeting CAR-Ms phagocytose melanoma cells in vitro, and that this CAR-M-mediated phagocytosis is specific to CSPG4-expressing cells." (PMID 40082557, 2025). "Preclinical studies have identified various potential future targets for targeted melanoma therapy, including CD126, chondroitin sulfate proteoglycan 4 (CSPG4), tandem CD70 and B7-H3, and αvβ3 integrin." (PMID 38399429, 2024). "Later attempts at utilising anti-idiotypic mAbs in a phase I trial of 25 patients with stage IV melanoma employed the MK2-23 anti-idiotypic mAb, which recognises the 763.74 anti-CSPG4 clone." (PMID 39409881, 2024). "Current preclinical studies have identified new potential targets for precision melanoma therapy, including CD126, chondroitin sulfate proteoglycan 4 (CSPG4), tandem CD70 and B7-H3, and αvβ3 integrin." (PMID 38399429, 2024). "The two pathways activated by CSPG4 are the focal adhesion kinase (FAK) pathway and, particularly pertinent in melanoma, the mitogen-activated protein kinase (MAPK) pathway." (PMID 39409881, 2024). "When co-cultured with a melanoma cell line, CSPG4-targeting CAR T cells proliferated, produced cytokines (such as IFN-γ and TNF-α), and specifically lysed CSPG4-expressing cancer cells." (PMID 39409881, 2024). "Chondroitin sulfate proteoglycan 4 (CSPG4) is a transmembrane protein overexpressed in solid tumours, including melanoma, with restricted expression in normal tissues, potentially fulfilling key criteria as a promising therapeutic target." (PMID 39409881, 2024). "Circulating CSPG4-reactive CD4+ T cells have been detected in healthy individuals and patients with melanoma." (PMID 39409881, 2024). "Based on overexpression in solid tumours such as melanoma or triple-negative breast cancer (TNBC) but restricted expression in normal tissues, CSPG4 has been proposed as a promising therapeutic target." (PMID 39409881, 2024). "Chondroitin sulfate proteoglycan 4 (CSPG4) is a type I transmembrane protein widely expressed across multiple malignant tumors, including melanoma, triple-negative breast cancer, mesothelioma, and sarcoma." (PMID 39506843, 2024).